SCUBE1 (signal peptide, CUB domain and EGF like domain containing 1)
Diseases named in the same sentence as SCUBE1 in open-access papers (continued):
Sharing a sentence is not in itself a finding about the gene and the disease.
cardiovascular disease (4 papers, 2018 to 2025). "One study reported that SCUBE-1 functions as a platelet endothelial adhesion molecule and mediates the pathological process in cardiovascular diseases." (PMID 41300915, 2025). "In several ischemic contexts, SCUBE1 is released into plasma and may be useful as biomarker for cardiovascular diseases." (PMID 37237303, 2023). "Together, these observations suggest that SCUBE1 might function as a key platelet-endothelial adhesion molecule in the pathophysiological development of cardiovascular disease." (PMID 37237303, 2023). "SCUBE1 levels are elevated in women with PCOS compared with those in healthy controls; thus, this protein may be an early biomarker of cardiovascular disease later in life." (PMID 30202624, 2018). "Circulating SCUBE1 levels are elevated in young, lean, glucose-tolerant women with PCOS compared with those in healthy controls; thus, this protein may be an early biomarker of cardiovascular disease later in life." (PMID 30202624, 2018).
tumor (4 papers, 2007 to 2025). "Our results indicated that PD‐L1 contributes to tumor progression in CRPC by modulating the expression of SCUBE1." (PMID 40923331, 2025). "We further elucidated through experimentation that PD‐L1 contributes to tumor progression in CRPC by modulating the expression of SCUBE1." (PMID 40923331, 2025). "According to the results of IHC, SCUBE1 was mainly expressed in the tumour stroma with higher expression in tumour tissues than that in normal tissues." (PMID 36348351, 2022). "The results showed that the tumour cell proliferation rate was significantly increased after coculture with CAFs2, but this effect disappeared when SCUBE1 expression was downregulated." (PMID 36348351, 2022). "We have identified tumor expression of Scube1 using a candidate-based approach, based upon its expression in a subset of mesenchyme that is known to be important in prostate development." (PMID 17922897, 2007). "Finally, we found that PD‐L1 contributes to tumor progression in CRPC by modulating the expression of SCUBE1." (PMID 40923331, 2025). "Although the SCUBE1 expression levels in various cells are higher than that in tumour cells, it cannot be determined whether SCUBE1 is enriched in the tumour stroma, since the scRNA database can only assess the intracellular expression." (PMID 36348351, 2022). "The region 22q13 contains approximately 242 genes, and thus genes other than Scube1 may be acting as tumor suppressors." (PMID 17922897, 2007). "The downregulation of Scube1 in CAFs compared with NPFs suggests that it may function as a tumor suppressor, although this remains to be experimentally confirmed." (PMID 17922897, 2007). "Overall, we can conclude that HCC tumour tissues and the circulatory system of HCC patients have high SCUBE1 expression." (PMID 36348351, 2022).
infection (2 papers, 2024 to 2025). The state of being infected such as from the introduction of a foreign agent such as serum, vaccine, antigenic substance or organism. "SCUBE1 was found to be involved in immune regulation, playing a role in the body’s response to inflammation and infection, which are common in DFU." (PMID 39543487, 2024). "The involvement of SCUBE1 in regulating immune responses suggests its critical role in DFU pathogenesis by influencing inflammation, which is essential for effective infection control and wound healing." (PMID 39543487, 2024).
SCUBE1 also shares sentences with these, for which no sentence is quoted: Arterial thrombosis (1 paper); atherosclerosis (1); endothelial dysfunction (1); hypercoagulability (1); hypertensive retinopathy (1); Insulin resistance (1); ischaemic heart disease (1); kidney disorder (1); myelodysplastic syndrome (1); myocardial infarction (1); Obesity (1); obstructive jaundice (1); osteoarthritis (1); psoriasis (1); renal cell cancer (1); rheumatoid arthritis (1); stem cell leukemia (1); Thromboembolism (1).